RIT2 (Ras like without CAAX 2)
Description:
Binds and exchanges GTP and GDP. Binds and modulates the activation of POU4F1 as gene expression regulator.
Synonyms: RIN; ROC2; RIBA
Tractability: Antibody: UniProt places it where antibodies can reach, with high confidence; its Gene Ontology location is reachable by antibodies, with high confidence. PROTAC: ubiquitination databases record sites on it; its protein half-life has been measured.
Gene: Protein-coding gene on chromosome 18 (42,743,218 to 43,115,719, reverse strand). Ensembl gene ENSG00000152214.
Subcellular location: Nucleus; Cell membrane
Subcellular location (Human Protein Atlas): Nucleoplasm; Cytosol; Golgi apparatus
Pathways (Reactome):
Signal Transduction: Signalling to p38 via RIT and RIN
Gene Ontology:
Molecular function: calmodulin binding; identical protein binding; protein binding; semaphorin receptor binding; GTP binding; GTPase activity; chromatin binding; G protein activity
Biological process: intracellular signal transduction; maintenance of protein location in cell; positive regulation of neuron projection development; regulation of endocytosis; chemical synaptic transmission; MAPK cascade; positive regulation of MAPK cascade; Ras protein signal transduction; regulation of calcium-mediated signaling; regulation of Cdc42 protein signal transduction; small GTPase-mediated signal transduction; adenylate cyclase-activating G protein-coupled receptor signaling pathway; negative regulation of neuron projection development; positive regulation of transcription by RNA polymerase II; signal transduction
Cellular component: membrane raft; neuron projection; nucleoplasm; nucleus; plasma membrane; cell body; cytoplasm; dendritic tree; membrane; synapse
Genetic constraint (gnomAD): Loss-of-function variants: 16 observed, 14.2 expected, observed/expected ratio (o/e) 1.13, 90% interval 0.76 to 1.68. The upper end of that interval is the gene's LOEUF score, 1.68, which puts it in group 6 of 6, group 1 being the genes least tolerant of losing a copy. Missense variants: 186 observed, 203.92 expected, observed/expected ratio (o/e) 0.91, 90% interval 0.81 to 1.03. Synonymous variants: 81 observed, 74.69 expected, observed/expected ratio (o/e) 1.08, 90% interval 0.9 to 1.3.
Homologues: Orthologues: chimpanzee RIT2 (100% identical), macaque RIT2 (99% identical), rabbit RIT2 (97% identical), guinea pig RIT2 (97% identical), dog RIT2 (96% identical), mouse Rit2 (92% identical), rat Rit2 (91% identical), Drosophila melanogaster Ric (59% identical). Paralogues in human: RIT1 (66% identical), RRAS2 (45% identical), KRAS (41% identical), RRAS (41% identical), MRAS (40% identical), NRAS (40% identical), HRAS (39% identical), RAP1A (38% identical), RAP1B (38% identical), RALB (38% identical), RALA (37% identical), RAP2A (37% identical), and 23 more.
Diseases named in the same sentence as RIT2 in open-access papers:
RIT2 is named in the same sentence as 17 diseases in open-access papers, as found by Europe PMC text mining. Sharing a sentence is not in itself a finding about the gene and the disease. The quoted sentences say what the papers report.
Parkinson disease (8 papers, 2012 to 2024). A progressive degenerative disorder of the central nervous system characterized by loss of dopamine producing neurons in the substantia nigra and the presence of Lewy bodies in the substantia nigra and locus coeruleus. "The rs12456492 variant in the RIT2 gene has been repeatedly associated with increased risk for Parkinson’s disease." (PMID 34305570, 2021). "We looked up the upstream and downstream locations of LINC00907 and found that the downstream Rit2 gene was associated with Parkinson's disease, schizophrenia, and autism." (PMID 33110425, 2020). "Furthermore, Rit2 is highly and preferentially expressed in dopaminergic neurons in the substantia nigra, and meta-analysis of genome-wide association studies identified RIT2 as a novel Parkinson disease susceptibility locus." (PMID 23805044, 2013). "In two distinct GWAS reports, RIT2 gene was identified as a new locus for both Parkinson's disease (PD) and autism spectrum disorder (ASD)." (PMID 36820223, 2023). "In the PPMI cohort, both MDS-Unified Parkinson's Disease Rating Scale II and motor PC1 progression were associated with RIT2 rs12456492." (PMID 36164437, 2022). "Of these 7, genome-wide studies have associated RIT2 and ANK1 with Parkinson’s and Alzheimer’s disease respectively." (PMID 25493648, 2014). "Genes showing similar co-expression patterns have been previously linked to Alzheimer’s (ANK1) and Parkinson’s disease (UBE2E2, PCMT1, HPRT1 and RIT2)." (PMID 25493648, 2014). "Recently, Ras-like without CAAX2 (RIT2) has been introduced as a genetic risk gene for neurological and psychiatric disorders such as Parkinson's disease (PD), schizophrenia, and ASD." (PMID 36820223, 2023).
autism (2 papers, 2019 to 2020). Persistent deficits in social interaction and communication and interaction as well as a markedly restricted repertoire of activity and interest as well as repetitive patterns of behavior. "Rit2 is involved in the ubiquitin E3 ligase growth factor pathway that affects mitochondrial dysfunction, which is linked with both schizophrenia and autism." (PMID 31213978, 2019). "Specifically for RIT2, evidence suggests that proteins interacting with RIT2 may cause or relate to similar clinical signs or diseases, which implied that RIT2 might be a potential candidate gene underlying several neurological diseases, such as PD, schizophrenia and autism." (PMID 31213978, 2019).
neuroblastoma (2 papers, 2021 to 2023). Neuroblastoma (NB) is the most common solid, extracranial childhood tumor. "Enhanced Rit2 expression rescues the G2019S-LRRK2-induced lysosomal defects, whereas the reduction of Rit2 levels in neuroblastoma cells and primary DA neurons induces defects in the ALP and specifically to lysosome biology." (PMID 36973269, 2023). "This indicates that enhanced Rit2 expression counteracts pS129-aSyn accumulation not only in recombinant neuroblastoma cell lines, but importantly also in an in vivo PD mouse model, providing effective neuroprotection in a non-LRRK2 modeling paradigm." (PMID 36973269, 2023). "Here we report that Rit2 reduces phosphorylation levels of S1292-LRRK2 in recombinant neuroblastoma cells and is neuroprotective in animals with no LRRK2 mutations, therefore we assessed the impact of Rit2 on S1292 autophosphorylation in the mouse DA neurons." (PMID 36973269, 2023). "Nucleofection efficiency was similar to the other neuroblastoma cell lines, as protein and mRNA levels of Rit2 were correctly augmented by overexpression." (PMID 36973269, 2023). "Taken together these results reveal that Rit2 does not affect the overall autophagic flux, but rescues the morphological and functional deficits of the lysosomes we previously identified in G2019S-LRRK2 neuroblastoma cells." (PMID 36973269, 2023).
schizophrenia (2 papers, 2019 to 2020). A major psychotic disorder characterized by abnormalities in the perception or expression of reality. "Several recent studies have suggested that the rit2 gene might be involved in the pathogenesis of schizophrenia." (PMID 31213978, 2019).
Alzheimer disease (1 paper, 2014). A progressive, neurodegenerative disease characterized by loss of function and death of nerve cells in several areas of the brain leading to loss of cognitive function such as memory and language. "We note that Ras-Like without CAAX 2 (RIT2) has been recently associated with PD in two large genomic studies and Ankyrin 1, erythrocytic (ANK1) shows altered methylation and expression in Alzheimer’s disease." (PMID 25493648, 2014).
autism spectrum disorder (1 paper, 2023). A spectrum of developmental disorders that includes autism, and Asperger syndrome. "Recent studies have shown that Ras-like without CAAX2 (RIT2) polymorphism is a susceptible factor for Parkinson's disease (PD) and autism spectrum disorder (ASD)." (PMID 36820223, 2023).
bladder exstrophy (1 paper, 2023). Bladder exstrophy (or classic bladder exstrophy; CEB) is a congenital genitourinary malformation belonging to the spectrum of the exstrophy-epispadias complex (EEC) and is characterized by an evaginated bladder plate, epispadias and an anterior defect of the pelvis, pelvic floor and abdominal wall. "A closer analysis suggests a few gene networks that are involved in the pathogenesis of bladder exstrophy; the WNT‐signaling pathway, the chromosome 22q11 region, the RIT2 and POU families, and involvement of the Golgi apparatus." (PMID 36349425, 2023).
infection (2 papers, 2018 to 2020). The state of being infected such as from the introduction of a foreign agent such as serum, vaccine, antigenic substance or organism. "The viability of RIT2-KO cells was lower than that of control cells, but lentiviral overexpression of RIT2 (multiplicity of infection of 10) increased the cell viability." (PMID 30137437, 2018).
RIT2 also shares sentences with these, for which no sentence is quoted: Parkinson (2 papers); bacterial infection (1); cancer (1); degenerative diseases (1); epilepsy (1); hereditary ataxia (1); neurological diseases (1); nicotine dependence (1); pheochromocytoma (1).